PSTPIP1 (proline-serine-threonine phosphatase interacting protein 1)
Description:
Involved in regulation of the actin cytoskeleton. May regulate WAS actin-bundling activity. Bridges the interaction between ABL1 and PTPN18 leading to ABL1 dephosphorylation. May play a role as a scaffold protein between PTPN12 and WAS and allow PTPN12 to dephosphorylate WAS. Has the potential to physically couple CD2 and CD2AP to WAS. Acts downstream of CD2 and CD2AP to recruit WAS to the T-cell:APC contact site so as to promote the actin polymerization required for synapse induction during T-cell activation (By similarity). Down-regulates CD2-stimulated adhesion through the coupling of PTPN12 to CD2. Also has a role in innate immunity and the inflammatory response. Recruited to inflammasomes by MEFV. Induces formation of pyroptosomes, large supramolecular structures composed of oligomerized PYCARD dimers which form prior to inflammatory apoptosis. Binding to MEFV allows MEFV to bind to PYCARD and facilitates pyroptosome formation. Regulates endocytosis and cell migration in neutrophils.
Synonyms: CD2BP1; PSTPIP; CD2BP1L; CD2BP1S; H-PIP; PAPAS; AICZC; PAPA
Tractability: Antibody: UniProt places it where antibodies can reach, with high confidence; its Gene Ontology location is reachable by antibodies, with high confidence; the Human Protein Atlas places it where antibodies can reach. PROTAC: ubiquitination databases record sites on it; its protein half-life has been measured.
Gene: Protein-coding gene on chromosome 15 (76,993,325 to 77,037,475, forward strand). Ensembl gene ENSG00000140368.
Subcellular location: Cytoplasm; Cell membrane; Cell projection, uropodium; Cytoplasm, cytoskeleton; Cytoplasm, perinuclear region; Cell projection, lamellipodium; Cleavage furrow
Subcellular location (Human Protein Atlas): Cytosol; Plasma membrane
Pathways (Reactome):
Disease: Purinergic signaling in leishmaniasis infection
Immune System: The NLRP3 inflammasome
Gene Ontology:
Molecular function: identical protein binding; protein binding
Biological process: cell adhesion; signal transduction
Cellular component: cytoplasm; cytosol; membrane; plasma membrane; cleavage furrow; cytoskeleton; lamellipodium; perinuclear region of cytoplasm; uropod
Genetic constraint (gnomAD): Loss-of-function variants: 66 observed, 57.04 expected, observed/expected ratio (o/e) 1.16, 90% interval 0.95 to 1.42. The synonymous counts are far from expectation, so gnomAD's model fits this gene poorly and the ratio says little. Missense variants: 603 observed, 499.42 expected, observed/expected ratio (o/e) 1.21, 90% interval 1.13 to 1.29. Synonymous variants: 266 observed, 198.81 expected, observed/expected ratio (o/e) 1.34, 90% interval 1.21 to 1.48.
Homologues: Orthologues: pig PSTPIP1 (91% identical), macaque PSTPIP1 (89% identical), mouse Pstpip1 (88% identical), rat Pstpip1 (86% identical), dog PSTPIP1 (82% identical), guinea pig PSTPIP1 (76% identical), chimpanzee PSTPIP1 (70% identical), tropical clawed frog pstpip1 (60% identical), zebrafish pstpip1a (56% identical), zebrafish pstpip1b (39% identical). Paralogues in human: PSTPIP2 (36% identical), FCHO2 (22% identical), FCHO1 (20% identical), GAS7 (18% identical), SGIP1 (11% identical).
Diseases named in the same sentence as PSTPIP1 in open-access papers:
PSTPIP1 is named in the same sentence as 50 diseases in open-access papers, as found by Europe PMC text mining. Sharing a sentence is not in itself a finding about the gene and the disease. The quoted sentences say what the papers report.
pyoderma gangrenosum (40 papers, 2008 to 2025). An idiopathic, rapidly evolving, and severely debilitating disease occurring most commonly in association with chronic ulcerative colitis. "A PSTPIP1 pathogenic variant was recently identified in a patient with proctitis, pyoderma gangrenosum, HS and fever (dubbed “PPHSF” syndrome)." (PMID 35401657, 2022). "Previous reports have demonstrated that mutations in PSTPIP1 result in human pyogenic sterile arthritis, pyoderma gangrenosum, pyogenic arthritis, pyoderma gangrenosum, and acne syndrome, a dominant autosomal autoinflammatory diseases." (PMID 34262554, 2021). "Missense mutations in PSTPIP1/CD2BP1 cause a dominantly inherited autoinflammatory syndrome called pyogenic arthritis, pyoderma gangrenosum, and acne (PAPA)." (PMID 31456795, 2019). "Pyrin, which is mutated in FMF, interacts with PSTPIP1, which causes pyogenic sterile arthritis, pyoderma gangrenosum, and acne (PAPA) syndrome and PSTPIP1-associated myeloid-related proteinemia inflammatory (PAMI)." (PMID 30255357, 2018). "Thirdly, a novel mutation in the PSTPIP1 gene resulted in a case of pyoderma gangrenosum, acne and ulcerative colitis (PAC)." (PMID 30619323, 2018). "Pyogenic arthritis, pyoderma gangrenosum, and acne are caused by mutation in the PSTPIP1 gene, involved in regulation of the actin cytoskeleton." (PMID 29080202, 2017). "Pyogenic arthritis, pyoderma gangrenosum and acne (PAPA) syndrome is caused by mutations in the genes encoding proline-serine-threonine phosphatase interacting protein 1 (PSTPIP1)." (PMID 27187378, 2016). "Interestingly, PEST-PTPs play an important role in another autoinflammatory disorder named PAPA syndrome (pyogenic sterile arthritis, pyoderma gangrenosum, and acne) which is caused by the loss of their binding to PSTPIP1, a homologue of PSTPIP2." (PMID 36605205, 2022). "Various pyogenic disorders starting in childhood can also be considered inflammasome-related diseases, and—particularly—a rare autosomal-dominant pathology caused by mutations in the PSTPIP1 gene, named “pyogenic arthritis, pyoderma gangrenosum and acne (PAPA) syndrome”, is the most relevant." (PMID 33999387, 2021). "Different data show that genetic metabolism errors are responsible for some of CRMO syndromes, for example, the PSTPIP1 gene is associated with pyogenic arthritis, pyoderma gangrenosum and acne (PAPA) syndrome as well as defects in LPIN2 result in Majeed syndrome." (PMID 30053822, 2018). "Interestingly, PAPA syndrome (pyogenic sterile arthritis, pyoderma gangrenosum and acne) caused by mutations in the cytoskeletal adapter PSTPIP1 (which binds to WASp) shares cytoskeletal features with WAS and is also associated with overt IL-1β production." (PMID 29146903, 2017). "Mutations in PSTPIP1 may cause pyoderma gangrenosum and acne syndrome (PAPA); the PAPA-associated mutations A230T, E250Q, and E250K may increase PSTPIP1 phosphorylation, which further activates the pyrin inflammasome by increasing ASC-mediated inflammasome assembly." (PMID 34177950, 2021). "For example, mutations in proline-serine-threonine phosphatase-interacting protein 1 (PSTPIP1), which increases its binding to pyrin, promote excessive inflammasome activation and result in pyogenic arthritis, pyoderma gangrenosum, and acne (PAPA) syndrome." (PMID 41087719, 2025). "Gain of function mutations affecting the proline-serine-threonine phosphatase interacting protein 1 (PSTPIP1) gene are responsible for the “pyogenic arthritis, pyoderma gangrenosum and acne” (PAPA) syndrome, a rare AD inherited autoinflammatory disease." (PMID 38250061, 2023). "The PSTPIP1 gene mutations, affecting proteins of the inflammasome, have been proven in PAPASH (pyoderma gangrenosum, acne, arthritis, and HS), and PASH (pyoderma gangrenosum, acne, suppurative hidradenitis) syndromes." (PMID 35409118, 2022).
pyoderma gangrenosum (continued). "It has been proved that PSTPIP1 is the pathogenetic gene for pyogenic arthritis, pyoderma gangrenosum, and acne (PAPA) syndrome, an autosomal dominantly inherited monogenic autoinflammatory disease." (PMID 35422809, 2022). "The causative gene product of pyogenic arthritis, pyoderma gangrenosum, and acne (PAPA) syndrome is proline-serine-threonine phosphatase-interacting protein 1 (PSTPIP1) (also called CD2-binding protein 1 (CD2BP1))." (PMID 34635190, 2021). "Pyogenic arthritis, pyoderma gangrenosum and acne (PAPA) is an AD disease, caused by gain-of-function mutations of proline-serine-threonine phosphatase interacting protein 1 (PSTPIP1) gene, located on chromosome 15." (PMID 34198614, 2021). "Pyogenic arthritis, pyoderma gangrenosum, and acne (PAPA) syndrome is a rare autosomal dominant autoinflammatory syndrome caused by missense mutations in the PSTPIP1 gene located in chromosome 15." (PMID 32737687, 2020). "There is now evidence of mutations to the PSTPIP1 gene in cases of pyoderma gangrenosum, acne and suppurative hidradenitis (PASH) and pyogenic arthritis, pyoderma gangrenosum, acne and suppurative hidradenitis (PAPASH) syndromes." (PMID 30619323, 2018). "Some cases of HS are associated with syndromes, including pyoderma gangrenosum, acne, and suppurative hidradenitis (PASH) syndrome, related to mutations in proline-serine-threonine-phosphatase protein 1 (PSTPIP1)." (PMID 28794864, 2017). "Another similar syndrome, pyogenic arthritis, pyoderma gangrenosum, acne, and hidradenitis suppurativa (PAPASH) syndrome, is also associated with PSTPIP1 gene mutations." (PMID 28794864, 2017). "PAPA syndrome (pyogenic arthritis, pyoderma gangrenosum, and acne) is an autosomal dominant arising from PSTPIP1 gene mutation in the SH3 domain of PSTPIP1." (PMID 25956236, 2015). "PAPA syndrome (Pyogenic Arthritis, Pyoderma gangrenosum, and Acne) is an autosomal dominant, hereditary auto-inflammatory disease arising from mutations in the PSTPIP1/CD2BP1 gene on chromosome 15q." (PMID 21532836, 2010). "Pyogenic sterile arthritis, pyoderma gangrenosum and acne syndrome is caused by mutations in the CD2BP1 or PSTPIP1 (15q22-24) gene." (PMID 20813071, 2010). "Mutations in PSTPIP1 cause PAPA syndrome (Pyogenic sterile Arthritis, Pyoderma gangrenosum, and Acne), an autoinflammatory disease." (PMID 19584923, 2009). "Mutations in the PSTPIP1 gene result in PAPA Syndrome (Pyogenic sterile Arthritis, Pyoderma gangrenosum, and Acne, another autoinflammatory disease with severe skin and joint involvement." (PMID 19584923, 2009). "Similarly, the proline-serine-threonine phosphatase interacting protein 1 (PSTPIP) mutation in pyogenic arthritis, pyoderma gangrenosum, and acne (PAPA) syndrome causes greater activation of the pyrin inflammasome and elevated IL-1β levels." (PMID 37692753, 2023). "Pathogenic variants in PSTPIP1 (proline-serine-threonine phosphatase interacting protein 1) cause PAPA syndrome an autosomal dominant autoinflammatory disorder characterized by pyogenic arthritis, pyoderma gangrenosum, and severe cystic acne (MIM 604,416)." (PMID 35486341, 2022). "Finally, pyogenic arthritis, pyoderma gangrenosum, and acne (PAPA) syndrome, caused by PSTPIP1 gene mutations, is characterized by the constellation of arthritis, pyoderma gangrenosum and severe cystic acne." (PMID 36034552, 2022). "Pyoderma gangrenosum (and cystic acne) are characterized by neutrophil infiltration; given the strong PSTPIP1 expression in neutrophils we hypothesize that this is at least in part secondary to an intrinsic mechanism in these cells." (PMID 21532836, 2010). "PSTPIP1 mutations have been detected in autoinflammatory syndromes associated with HS, namely, PASH (pyoderma gangrenosum, acne, and hidradenitis suppurativa) syndrome and PAPASH (pyogenic arthritis, pyoderma gangrenosum, acne, and Hidradenitis suppurativa) syndrome." (PMID 39606016, 2024).
pyoderma gangrenosum (continued). "Interestingly, mutations in the F-BAR domain (E250Q and A230T) of CD2BP1/PSTPIP1 are associated with the PAPA syndrome (acronym for Pyogenic Arthritis, Pyoderma gangrenosum, and Acne), a rare inherited auto-inflammatory disease, and to disrupt the binding of PTP PEST." (PMID 28243699, 2017). "Notably, also, cases with isolated pyoderma gangrenosum or Crohn’s disease-associated pyoderma gangrenosum, have thus far proven negative for PSTPIP1 mutations." (PMID 21532836, 2010). "Mutations involving different autoinflammatory genes (MEFV, NLRP3, NLRP12, NOD2, LPIN2, and PSTPIP1) have been reported in syndromic HS [pyoderma gangrenosum, acne, and hidradenitis suppurativa (PASH) syndrome] as well as in pyoderma gangrenosum (PG), a prototypic neutrophilic dermatosis." (PMID 32425927, 2020). "Syndromic HS forms, including Pyoderma gangrenosum, Acne, and Suppurative Hidradenitis (PASH) and Pyogenic Arthritis, Pyoderma gangrenosum, Acne, and Suppurative Hidradenitis (PAPASH) syndromes, involve genetic changes in PSTPIP1, NLRP3, and other autoinflammatory genes." (PMID 40458403, 2025).
acne (37 papers, 2008 to 2025). An inflammatory process of the sebaceous glands which is characterized by comedones, nodules, papules and/or pustules on the skin. "Of note, the hereditary autosomal dominant form of PG known as pyogenic arthritis, PG, and acne (PAPA syndrome) is associated with mutations in proline–serine–threonine phosphatase interacting protein 1 (PSTPIP1)." (PMID 37475852, 2023). "PAPASH syndrome is an autoinflammatory syndrome clinically characterized by pyogenic arthritis, pyoderma gangrenosum (PG), acne, and hidradenitis suppurativa (HS) associated with mutations in the PSTPIP1 gene." (PMID 25243162, 2014). "Some case-reports about an autosomal dominant, auto-inflammatory disease, known as PAPA-syndrome (pyogenic arthritis, PG and acne) showed an association to mutations in the PSTPIP1/CD2BP1 gene on chromosome 15q." (PMID 24010984, 2013). "Conditions included in this class are PAPA (pyogenic arthritis, pyoderma gangrenosum, and acne conglobata), PASH (pyoderma gangrenosum, acne, and suppurative hidradenitis), and PAMI (PSTPIP1-associated myeloid-related proteinemia inflammatory syndrome)." (PMID 38187026, 2024). "The refractory monogenic inflammatory disorder, PAPA, resulted from a dominant mutation with the proline-serine-threonine phosphatase interacting protein 1 (PSTPIP1) gene and is characterized by acne and skin ulceration." (PMID 35885055, 2022). "A diagnosis of pyoderma gangrenosum, acne, and suppurative hidradenitis syndrome secondary to a PSTPIP1 gene mutation was declined, as the patient had never experienced acne lesions, and the HS was mild." (PMID 40547405, 2025). "This suggests that PSTPIP1 may activate shared pathways related to both HS and pyogenic arthritis, in adddition to PG and acne." (PMID 38031879, 2024). "As distinct from PAPA (pyogenic sterile arthritis, PG, and acne) syndrome, no mutation was detected in the PSTPIP1 gene in PASH syndrome." (PMID 25243162, 2014). "The dermatologic signs of PG and acne with pyogenic sterile arthritis, PG, and acne (PAPA) syndrome have been defined as an autosomal dominant autoinflammatory syndrome caused by mutations in the proline-serine-threonine-phosphatase interactive protein 1 (PSTPIP1) gene." (PMID 25243162, 2014). "Furthermore, PSTPIP1-associated inflammatory diseases also demonstrate pyogenic arthritis, PG, acne, and hidradenitis suppurativa syndrome (PAPASH), pyogenic arthritis, PG, and acne-like syndrome (PAPA-like), as well as PG, acne, and ulcerative colitis syndrome (PAC)." (PMID 34620178, 2021). "Additionally, dysregulation of PSTPIP1‐associated pathogenic pathways might be exacerbated by the involvement of multiple genetic factors and interactions with environmental factors, such as smoking contributing to HS development, in PSTPIP1‐mutation negative PG, HS, pyogenic arthritis, and acne." (PMID 38031879, 2024).
pyogenic arthritis (33 papers, 2008 to 2025). "Mice ectopically expressing the PAPA-associated PSTPIP1 A230T mutant protein show elevated levels of circulating cytokines implicated in active PG, but they fail to develop skin inflammation and arthritis, specific to PAPA syndrome." (PMID 37475852, 2023). "More recently, patients with PSTPIP1 mutations causing neutrophilic skin rashes and arthritis were found to have chronic elevation of IL-18." (PMID 36096831, 2022). "Given that LYP is involved in inflammatory autoimmune diseases such as arthritis and lupus, we wanted to see how PSTPIP1 mutations affected its interaction with LYP." (PMID 35152348, 2022). "Most of these mutations lie in PSTPIP1 F-BAR domain, which binds to LYP, a protein tyrosine phosphatase associated with arthritis and lupus." (PMID 35152348, 2022). "Pyogenic arthritis, pyoderma gangrenosum and acne (PAPA) is a rare autoinflammatory disease caused by mutations in the gene that codes for the proline–serine–threonine phosphatase interacting protein 1 (PSTPIP1)." (PMID 35152348, 2022). "PAPA syndrome (pyogenic arthritis, pyoderma gangrenosum, and acne, OMIM #604416) is a hereditary autosomal dominant autoinflammatory syndrome caused by gain-of-function mutations in the PSTPIP1 gene." (PMID 28588486, 2017).
autoinflammatory syndrome (10 papers, 2013 to 2026). A group of disorders of the innate immune system characterized by attacks of seemingly unprovoked inflammation without significant levels of either autoantibodies or autoreactive T cells more characteristic of autoimmune disease. "Other autoinflammatory syndromes caused by mutations in the PSTPIP1 gene, such as PAMI, PASH, PAPASH, PsAPASH, PAC, or PASS syndrome, have recently been included in the group of PAPA spectrum disorders." (PMID 34745107, 2021). "Recently, a third auto-inflammatory syndrome was identified to be caused by mutations in the PSTPIP1 gene and alterations in the PSTPIP1-pyrin interaction: hyperzincemia and hypercalprotectinemia (Hz/Hc)." (PMID 28243699, 2017). "Mutations in the gene PSTPIP1 may cause several different autoinflammatory syndromes, but the mechanisms by which distinct PSTPIP1 mutations lead to these differing phenotypes are not fully understood." (PMID 42007463, 2026). "From medical history of unexplained recurrent fever with persistently increased inflammatory markers, we suspected autoinflammatory syndrome and performed targeted exome sequencing, which revealed pathogenic known mutation on his PSTPIP1 gene, which caused protein change (E275K)." (PMID 36096831, 2022). "In a previous study, using a next generation sequencing approach, we found many rare variants and some functional polymorphisms in genes related to autoinflammatory syndromes (AID): CECR1, MEFV, MVK, NLRP3, NOD2, PSTPIP1 and TNFRSF1A in our BD cohort." (PMID 30808881, 2019).
familial Mediterranean fever (7 papers, 2008 to 2023). Familial Mediterranean fever (FMF) is an autoinflammatory disorder characterized by recurrent short episodes of fever and serositis resulting in pain in the abdomen, chest, joints and muscles. "Again by a two-hybrid screen, PSTPIP1 was found to interact with pyrin, a protein mutated in a systemic auto-inflammatory disease called familial Mediterranean fever (FMF)." (PMID 28243699, 2017). "PSTPIP1 binds to pyrin and mutations in pyrin result in familial Mediterranean fever (FMF), a related autoinflammatory disorder." (PMID 19584923, 2009). "The data presented here provide new insight into the biology of PSTPIP1, the molecule mutated in PAPA syndrome, and clarify the nature of its interaction with pyrin, the protein mutated in familial Mediterranean fever." (PMID 19584923, 2009). "Hereditary mutations in pyrin, the causative for Familial Mediterranean fever (FMF) and in PSTPIP1, a pyrin interacting protein responsible for Pyogenic arthritis, pyoderma gangrenosum, and acne syndrome (PAPA), are responsible for impaired regulation of IL-1β maturation." (PMID 20482797, 2010).